RNU6-822P (RNA, U6 small nuclear 822, pseudogene)
Gene: Small nuclear RNA gene on chromosome 3 (20,268,965 to 20,269,070, reverse strand). Ensembl gene ENSG00000199577.
Homologues: Orthologues: chimpanzee U6 (99% identical), mouse Gm25473 (89% identical), mouse Gm23714 (86% identical). Paralogues in human: RNU6-774P (92% identical), RNU6-21P (90% identical), RNU6-28P (90% identical), RNU6-33P (90% identical), RNU6-38P (90% identical), RNU6-468P (90% identical), RNU6-86P (90% identical), RNU6-1 (89% identical), RNU6-11P (89% identical), RNU6-2 (89% identical), RNU6-37P (89% identical), RNU6-3P (89% identical), and 1289 more.